SLC2A1 (solute carrier family 2 member 1)
Diseases named in the same sentence as SLC2A1 in open-access papers (continued):
Sharing a sentence is not in itself a finding about the gene and the disease.
cancer (continued). "The use of glucose transporters (such as SLC2A1) in 18F-deoxyglucose positron emission tomography is a commonly used imaging technique in medical imaging, suitable for the diagnosis of various cancers." (PMID 39850557, 2024). "Cancer cells often overexpress glucose transporters such as SLC2A1/GLUT1 and SLC2A3/GLUT3 to take in large amounts of extracellular glucose to support their high rates of proliferation." (PMID 39406918, 2024). "Wang and his colleagues comprehensively summarized the prognostic role of SLC2A1 in pan-cancer and found that SLC2A1 is able to be overexpressed in a wide range of tumors and is associated with a poor prognosis in patients." (PMID 38517922, 2024). "LSH can aggravate cancer due to its ability of inhibit ferroptosis via the activation of metabolism-related genes as solute carrier family 2 member 1 (SLC2A1/GLUT1) and FADS2 both in vitro and in vivo." (PMID 37132605, 2024). "Increased levels of SLC2A1 enhance the absorption of glucose in cancer cells, supplying ample resources for glycolysis." (PMID 38965505, 2024). "GLUT1 (SLC2A1) is a facilitated-diffusion glucose transporter expressed by many cancer cells to fuel their increased rates of glycolysis." (PMID 39060287, 2024). "Consistent with this, increased expression of the major glucose transporter in cancer cells, glucose transporter 1 (GLUT1) (also known as SLC2A1), has been associated with increased proliferation and consequent poor prognosis." (PMID 38785550, 2024). "GLUT1 oscillation was not ablated by MYC in any of the cell lines, and it was only upregulated by MYC in SHEP, in contrast to previous reports that MYC transcriptionally upregulates SLC2A1 in other cancer models." (PMID 37639465, 2023). "GLUT1 (SLC2A1) has remained the main focus of cancer research, as this transporter plays a crucial role in the accelerated glucose uptake in cancer cells." (PMID 36839686, 2023). "Meanwhile, cancer cells express SLC2A1 at much higher levels on their cell membrane than normal cells, thereby selectively and excessively take up more glucose and provide a basis for promoting glycogen synthesis and accumulation." (PMID 37443106, 2023). "Solute carrier family 2 member 1 (SLC2A1) is a key factor for glucose transport and metabolism in cancer cells." (PMID 37180166, 2023). "In this study, data from public databases and our own data convincingly showed that the expression of SLC2A1 was significantly increased in pan-cancer and conferred a poor prognosis." (PMID 36358765, 2022). "Cancer cells require abundant glucose to meet the energy demands of rapidly proliferating cells, hence epigenetically silencing SLC2A1 using crocodile serum provides new strategies for the sensitization of cancer cells to chemo/radiotherapy." (PMID 35622738, 2022). "To study why SLC2A1 is highly expressed in pan-cancer, we performed genetic alteration, DNA promoter methylation, and RNA m6A methylation analyses." (PMID 36358765, 2022). "The expression of the SLC2A family is different in cancer, and the amount of SLC2A1 is enhanced in CC, which can predict poor prognosis and clinical characteristics." (PMID 36246625, 2022). "Although SLC2A1 plays an important role in the growth of many cancers, pan-cancer analysis allows us to more comprehensively and systematically understand the function and role of SLC2A1 in cancers." (PMID 36358765, 2022). "The protein expression levels of SLC2A1 showed abnormalities in all 10 cancers in the protein expression data provided by CPTAC." (PMID 36712872, 2022). "OncoPrint showed that the overall genetic alteration rate of SLC2A1 in cancers was relatively low (only 1.8%)." (PMID 36358765, 2022). "To comprehensively explore SLC2A1 function in cancer, we subsequently performed GSEA and constructed protein interaction networks." (PMID 36712872, 2022).
cancer (continued). "In this project, we predicted the high expression of SLC2A1 in a variety of cancers by analyzing Oncomine database and TCGA cohort." (PMID 35399515, 2022). "Cancer cells compete with immune cells for glucose uptake (by SLC2A1/GLUT1), produce lactic acid (by LDHA), and generate an acidic extracellular milieu (through the activity of CA9), all of which are immunosuppressive." (PMID 35499076, 2022). "This suggests that aberrant SLC2A1 expression in these cancers most likely influences the expression profile of immune checkpoints and thus alters the therapeutic effect of ICB." (PMID 36712872, 2022). "According to this, we calculated the difference in TIDE scores between the high and low SLC2A1 expression groups to explore the potential immune checkpoint blocker response of SLC2A1 on immunotherapy in these cancers." (PMID 36712872, 2022). "Most m6A-methylation-related genes positively correlated with the expression of SLC2A1 in 33 TCGA cancers." (PMID 36358765, 2022). "Our study provides a comprehensive and systematic analysis of the role of SLC2A1 in human cancers, investigates its differences and commonalities among different cancer species, and explores its potential as a pan-cancer biomarker." (PMID 36712872, 2022). "We used two methods, Kaplan–Meier and univariate Cox regression analyses, to evaluate the prognostic value of SLC2A1 in pan-cancer." (PMID 36358765, 2022). "Enhanced glycolysis is a major feature of cancer glycometabolism, and SLC2A1 is one of the pivotal genes in cancer glycometabolism." (PMID 36358765, 2022). "Among the 50 HALLMARK pathways associated with cancer, SLC2A1 was significantly associated with MTORC1_SIGNALING, HYPOXIA, and EPITHELIAL_MESENCHYMAL_TRANSITION in most cancers." (PMID 36712872, 2022). "Collectively, our study reveals the role of SLC2A1 as a powerful prognostic marker predicting immunotherapeutic efficacy for pan-cancer and explores its potential mechanisms." (PMID 36712872, 2022). "In this study, we found that SLC2A1 was highly expressed in most cancers, and resulted in poor prognosis." (PMID 36358765, 2022). "Our results revealed the potential of SLC2A1 to be developed as a pan-cancer prognostic marker and immunotherapy evaluation marker." (PMID 36712872, 2022). "SLC2A1 codes for the glucose transporter GLUT1, which is one of the proteins responsible for the increased aerobic glycolysis in several cancers." (PMID 35886000, 2022). "In LUAD, however, PFS was higher in the SLC2A1 duplicated group than in the normal and deleted groups, in contrast to the results of analyses in other cancer types." (PMID 36712872, 2022). "In the present study, we performed a comprehensive pan-cancer analysis of the role played by SLC2A1 in the development and progression of 33 cancers and its possible mechanisms." (PMID 36712872, 2022). "In this study, we explored the expression and prognosis of SLC2A1 in pan-cancer across multiple databases." (PMID 36358765, 2022). "Many SLC2A1 targeting miRNAs are downregulated in cancer cells, such as miR-148b in gastric cancer, miR-218 in bladder cancer, and miR-328 in colon cancer." (PMID 35755805, 2022). "Nevertheless, miR-328-3p also modulates the expression of other cancer-related genes, including SLC2A1, and synergistically inhibits cancer cell proliferation with chemotherapeutics." (PMID 35755805, 2022). "In our study, we used the single-cell database CancerSEA to explore the function of SLC2A1 in pan-cancer." (PMID 36358765, 2022). "Overall, however, these results suggest that SLC2A1 has the potential to be a pan-cancer prognostic biomarker." (PMID 36712872, 2022). "This suggested that the aberrant expression of SLC2A1 at the transcriptome level was not exclusively due to DNA promoter methylation, and we therefore explored the genetic alterations of SLC2A1 in pan-cancer." (PMID 36712872, 2022).
cancer (continued). "We also investigated the correlation of the SLC2A1 expression with MSI in pan-cancer: ACC, UVM, TGCT, SARC, STAD, and STES exhibited positive correlations; DLBC, KIPAN, GBMLGG, and PRAD exhibited negative correlations." (PMID 36358765, 2022). "Among the results of unpaired expression analysis provided by TIMER2.0, SLC2A1 was significantly upregulated in 14 cancer types and downregulated in two from TCGA." (PMID 36712872, 2022). "We assessed the prognostic value of SLC2A1 in pan-cancer by using Kaplan–Meier and Cox regression analyses." (PMID 36358765, 2022). "The relevance of SLC2A1 to immune infiltrating cells in pan-cancer was evaluated using the XCELL algorithm in combination with the TIMER2.0 database." (PMID 36712872, 2022). "In conclusion, we have performed a systematic and comprehensive analysis of the role of SLC2A1 in pan-cancer from multiple perspectives, including expression, prognosis, immunity, and biological function." (PMID 36712872, 2022). "In survival analyses of the SLC2A1 normal, duplicated, and deleted groups, the SLC2A1 duplicated group showed poor prognostic significance in several cancer types." (PMID 36712872, 2022). "The SLC2A1 gene is one of the key genes in cancer glycometabolism, which promotes the glycolysis of cancer cells, thus affecting their growth and metastasis." (PMID 36358765, 2022). "The overall genetic alteration frequency of SLC2A1 was 1.8% in pan-cancer, and the SLC2A1 promoter was hypomethylation in several cancers." (PMID 36358765, 2022). "As such, we investigated the associations between SLC2A1 expression and the two main types of immune modulators in human cancers to explore the potential function of SLC2A1 in immunotherapy." (PMID 36358765, 2022). "For example, elevated SLC2A1 (GLUT1) and SLC2A3 (GLUT3) have been associated with increased cancer metabolism." (PMID 35755805, 2022). "Third, using the MCPcounter algorithm, we found that SLC2A1 expression is positively correlated with neutrophils and CAFs in most cancers." (PMID 36358765, 2022). "Solute carrier family 2 member 1 (SLC2A1), which encodes the protein of a crucial glucose transporter, GLUT1, is overexpressed in diverse cancers, including PC, and correlated with poor clinical outcomes." (PMID 36057597, 2022). "To further validate the differential mRNA expression of SLC2A1, we comprehensively searched the GEO database and found a total of 20 relative datasets for the validation of the SLC2A1 pan-cancer analysis." (PMID 36358765, 2022). "This indicates that SLC2A1 is valuable in these cancers both as a long-term and short-term evaluation index." (PMID 36712872, 2022). "Multiple projects have indicated that the overexpression of SLC2A1 is closely related to the progression and metastasis of a variety of cancers." (PMID 35399515, 2022). "There was a strong correlation between SLC2A1 expression and stroma score, microenvironment score and immune score in most cancers." (PMID 36712872, 2022). "To preliminarily understand the expression of SLC2A1 in cancers, we first evaluated SLC2A1 mRNA expression in the TCGA-GTEx pan-cancer dataset." (PMID 36358765, 2022). "In contrast, SLC2A1 showed high expression in most cancers and low expression only in LAML and SKCM." (PMID 36712872, 2022). "First, we investigated DNA promoter methylation of SLC2A1 in pan-cancer by using the UALCAN database." (PMID 36358765, 2022). "The subcellular localization of SLC2A1 in cancer cells indicated that it is predominantly expressed in the plasma membrane." (PMID 36358765, 2022). "We collected 21 RNA m6A-methylation-related genes and performed pan-cancer correlation analysis between SLC2A1 and m6A-methylation-related genes, finding that they are significantly correlated in pan-cancer." (PMID 36358765, 2022). "SLC2A1-4 is upregulated in multiple cancer types (e.g., pancreatic, lung, and prostate), so there is significant interest in developing therapeutics targeting these transporters." (PMID 35755805, 2022).
cancer (continued). "Our findings showed that SLC2A1 is positively correlated with CD8+ T cells in some cancer types, but negatively correlated in other cancer types, suggesting that the effect of SLC2A1 on CD8+ T cells in the TME is complex." (PMID 36358765, 2022). "In our study, based on the TCGA-GTEx pan-cancer dataset, we found that SLC2A1 is highly expressed in most cancers compared with normal tissues, which we further confirmed via the GEO datasets, protein expression data from the HPA database, and our own data." (PMID 36358765, 2022). "STC2 and SLC2A1 were both involved in biological behaviors of many cancers, especially in HCC, through the modulation of mTOR signaling pathways." (PMID 34194464, 2021). "In the TCGA data (survival data: 391 cases), primary cancer tissues showed higher SLC2A1 expression than normal tissues (p = 0.005) (right)." (PMID 33735188, 2021). "Targeting SLC2A1 activity seems to be a promising strategy for the treatment of cancer with prominent hypoxic response and Warburg effect; however, utility of SLC2A1 inhibitors in MPNST is yet to be established." (PMID 33810575, 2021). "In our view, the central role of GLUT1 in cancer metabolism is reflected by the fact that the SLC2A1 gene encoding this glucose transporter is among the genes that show the strongest signals of purifying selection." (PMID 33427197, 2021). "Meanwhile, some evidence suggests that increased SLC2A1 expression is involved in glycolysis, cell proliferation, cancer growth, and metastasis, and is also related to the prognosis of LUAD." (PMID 34906142, 2021). "CircHECTD1 Lentivirus, miR-320-5p mimic, and SLC2A1 Lentivirus were transduced into cancer cells independently or together." (PMID 34079759, 2021). "It mainly affects the glycolytic pathway of cancer cells, and the inactivation of SLC2A1 eventually leads to apoptosis in vitro and in vivo." (PMID 34906142, 2021). "SLC2A1 is predicted to be involved in central carbon metabolism in cancer, HIF-1 signaling pathway, and adipocytokine signaling pathway." (PMID 34262595, 2021). "In view of the pro-oncogenic role of these proteins, it is noteworthy, that G6PD, MAPK13, PNCK, SLC16A3, and SLC2A1 are among the candidate cancer genes identified by forward genetic screens in mice." (PMID 33427197, 2021). "miR-328 is potentially capable of inhibiting SLC2A1 and consequently to regulate glycolytic activity of GLUT1 (anSLC2A1-encoded protein) in cancer cells." (PMID 34208601, 2021). "GLUT1, encoded by SLC2A1, is important in cancer development and is associated with poor prognosis in many cancers." (PMID 34872447, 2021). "The correlation of ZNF609, miR-378b, and SLC2A1 and their function in other cancers should be explored by more investigations." (PMID 34520391, 2021). "Glucose transporter member 1 (GLUT1, also known as SLC2A1) is a cell membrane glycoprotein responsible for glucose transport that is widely expressed across cell types and is overexpressed in many cancers." (PMID 34414229, 2021). "It is transported into cancer cells via different glucose transporters, mainly by glucose transporter 1 (GLUT1, encoded by SLC2A1) and metabolized via glycolysis." (PMID 33540663, 2021). "The transcriptional levels of the corresponding genes SLC2A1 through four in cancers are compared with those in normal samples by using ONCOMINE database." (PMID 34525987, 2021). "Results revealed that SLC2A1, 3, 4, 5, 6, 10, 13 and 14 were abnormally expressed in most cancer types." (PMID 34488531, 2021). "SLC2A1 has been indicated to be targeted by a certain number of miRNAs to mediate glycolysis in cancer, such as miR-148b in gastric cancer and miR-328 in colon cancer." (PMID 34520391, 2021). "Elevated glucose uptake in cancer cells is traditionally attributed to the glucose transporters SLC2A1 and SLC2A339." (PMID 31723131, 2019).
cancer (continued). "Cancer cells predominantly express SLC2A1 (GLUT1) and SLC2A3 (GLUT3) to transport glucose across the cell membrane and Hexokinase 1 and Hexokinase 2 to phosphorylate glucose." (PMID 31784510, 2019). "Knockdown of SLC2A1 has been shown to reverse the Warburg effect, decrease proliferation, and induce apoptosis in cancer cell lines and mouse xenografts." (PMID 29855388, 2018). "For example, Slc2a1 (Glut1) was clustered together with Cldn5 (claudin 5) and Abcg2 (the breast cancer protein) in both cerebral structures, but it was clustered closely only with Abcc1 (multidrug resistance protein 1) in the hippocampus." (PMID 30298005, 2018). "Semiquantitative evaluation revealed that the elevated expression of pAKT1, MTOR, pEIF4EBP1 and SLC2A1 in cancer was evident in 47 (94%), 30 (60%), 43 (86%) and 42 (84%) cases, respectively." (PMID 27512993, 2016). "Pathway results showed that seed genes PTGS2, HDAC1, JUN, and SLC2A1 were enriched in pathway in cancer, seed genes HDAC1 and CDC20 were involved in cell cycle, and seed gene MTHFR participated in methane metabolism." (PMID 27034707, 2016). "The glucose transporter isoform 1 (GLUT1; SLC2A1) is a key rate-limiting factor in the transport and metabolism of glucose in cancer cells." (PMID 26293674, 2015). "SLC2A1 is reported to be the primary glucose transporter of glucose metabolism, and the literature has shown that overexpression of SLC2A1 plays a critical role in the survival and rapid growth of the cancer cells in a suboptimal environment." (PMID 25705582, 2015). "The glucose transporter isoform 1 (GLUT1; SLC2A1) is a key rate-limiting factor in the transport of glucose into cancer cells." (PMID 26293674, 2015). "SLC2A1 mRNA expression was significantly higher in laryngeal TFG cancers with a total score ≥14 points than less aggressive ones (p = 0.021)." (PMID 25412955, 2015). "Considering SLC2A1 as a key rate-limiting factor for aerobic glycolysis in cancer cells, we next evaluated the effect of the MTOR signal cascade on aerobic glycolysis in HuH-7 cells." (PMID 25909713, 2015). "Recently, accumulated evidences demonstrated that high expression of SLC2A1 involves in the development of various carcinomas." (PMID 26193257, 2015). "Overall, the findings suggest that DERL3-hypermethylated cancer cells undergo glucose-dependent growth mediated by SLC2A1 that renders them highly sensitive to particular glycolysis inhibitors." (PMID 24699711, 2014). "SLC2A1 is the primary glucose transporter of glucose metabolism and overexpression of SLC2A1 has an important role in the survival and rapid growth of cancer cells in a suboptimal environment." (PMID 20540786, 2010). "Overexpression of SLC2A1 (GLUT-1) is a common feature of human cancers, including OSCC." (PMID 40362545, 2025). "Analysis of differentially expressed genes (DEGs) related to SLC2A1 showed significant correlations with multiple cancer - related pathways, such as carbon metabolism, thyroid hormone signaling, HIF - 1 signaling, membrane rafts, cerebral cortex development, and lactate metabolism." (PMID 40746529, 2025). "Therefore, targeting SLC2A1 to increase cancer cell autophagic flux holds potential clinical significance for cancer treatment." (PMID 40092704, 2025). "Notably, the elevated expression of SLC2A1, which encodes glucose transporter 1 (GLUT1), enhances cancer cell uptake of glucose, thereby reprogramming cellular metabolic pathways." (PMID 39992528, 2025). "Furthermore, HNSCC exhibited significantly elevated SLC2A1 mRNA expression compared with both normal esophageal mucosa and pan-cancer cell lines, and GLUT1 protein expression was observed to be higher in HNSCC tumors than in normal tissue." (PMID 40371988, 2025). "This indicates that high SLC2A1 expression may correlate with poor prognosis, highlighting its potential as a biomarker for personalized prognosis assessment in cancer treatment." (PMID 39992528, 2025).